EGFR (epidermal growth factor receptor)
Diseases named in the same sentence as EGFR in open-access papers (continued):
Sharing a sentence is not in itself a finding about the gene and the disease.
lung cancer (continued). "Small molecule inhibitors of kinases such as MEK, BRAF, EGFR, ALK, and KRAS promoted GSDME cleavage by CASP3 and resulted in lung cancer and melanoma regression." (PMID 35964070, 2022). "Conversely, in stage 1 patients with mutant EGFR, the LCF group exhibited worse survival than the single lung cancer group." (PMID 36233811, 2022). "In lung cancer, ALDH1A1 expressing cells are resistant to epidermal growth factor receptor (EGFR) tyrosine kinase inhibitor gefitinib." (PMID 35299840, 2022). "Since a continued investigation is recommended in the treatment pathway of HPV-positive head and neck cancer, detailed clinical information is needed to prove the effects of combined EGFR expression and HPV infections on clinical outcomes in lung cancer." (PMID 36358752, 2022). "The recommended treatments for stage IV EGFR-positive lung cancer are EGFR-tyrosine kinase inhibitor (TKI) monotherapy, EGFR-TKI plus cytotoxic combination chemotherapy, and EGFR-TKI plus anti-angiogenic combination therapy." (PMID 34643820, 2022). "Gefitinib and erlotinib inhibit the activation of EGFR-mediated PI3K/Akt/mTOR in A549, A549-gefitinib-resistant, KRAS-mutant H358, and H441 cells, leading to lung cancer cell apoptosis." (PMID 36547898, 2022). "We demonstrated that the expression levels of EGFR and CXCR4 on the sEVs well represented the ones in the source lung cancer cells." (PMID 35269297, 2022). "Interest in immunotherapy for patients with mutations increased after reports of upregulation of PD-L1 expression in mutant EGFR and ALK cells, and improved survival in mutant EGFR-driven murine lung cancer models with PD-1 axis blockade." (PMID 36291146, 2022). "However, whether and how STEP phosphatase contributes to the occurrence and development of tumor‐associated diseases, particularly the influence on the therapeutic effect of chemotherapeutic agents (such as EGFR‐TKIs applied in lung cancer), is still in the puzzle." (PMID 35838331, 2022). "The combination of the two induced EGFR (Epidermal Growth Factor Receptor) downregulation, whereas CAP inhibited lung cancer cells by inhibiting p-ERK and p-AKT." (PMID 35327329, 2022). "A mixture of three antibodies (called 3xmAbs) against EGFR, HER2 and HER3 was reported to be effective in lung cancer models resistant to second- and third-generation EGFR inhibitors, expressing mutant forms of EGFR." (PMID 36271429, 2022). "A dimensionless cell index indicated the number of surviving lung carcinoma A549 cells with a small amount of HER2 and high EGFR expression on the cell surface." (PMID 36713381, 2022). "Epidermal growth factor receptor (EGF-R), CD20 and MICA and MICB were expressed on the surface of A549 lung cancer cells and Raji B-cell lymphoma cells." (PMID 35967081, 2021). "To recapitulate the findings of EGFR expression in pleural endothelial cells, we cultured HUVEC with MAPF from lung cancer patients receiving thoracocentesis." (PMID 34680445, 2021). "Numerous studies have shown that mutations in certain proto-oncogenes and cancer suppressor genes, such as EGFR, KRAS, and BRAF, can be used as molecular markers in multiple lung cancers." (PMID 34109114, 2021). "METTL3 can promote the expression of multiple oncogenes such as BRD4, EGFR, TAZ, MAPKAPK2, and DNMT3A in human lung cancer cells." (PMID 34206803, 2021). "As for chromosome 7, which is widely reputed for its significant relations with the initiation and growth of lung cancer, EGFR and MET, for this chromosome, were found to play a major role with regard to lung cancer." (PMID 33503946, 2021). "Expression levels of the lung cancer marker proteins MYC, EGFR, and vimentin are also altered by the aberrant expression of BCL2L1." (PMID 34193120, 2021).
lung cancer (continued). "Here, we identify and characterize six patient-derived models of EGFR-mutant, MET-amplified lung cancer that have switched oncogene dependence to rely exclusively on MET activation for survival." (PMID 34516823, 2021). "Erlotinib (ER), an epidermal growth factor receptor (EGFR) tyrosine kinase inhibitor (TKI), is a targeted drug for lung cancer treatment." (PMID 34368128, 2021). "Epidermal growth factor receptor (EGFR) has a pivotal role in several tumors and among them lung cancer, breast cancer, and GBM." (PMID 34422883, 2021). "Since the level of EGFR was high in chemoresistant lung cancer, the EGFR-specific inhibitor gefitinib was administered to NCI-H460TXR and A549TXR cells to determine the sensitivity to gefitinib in paclitaxel-resistant lung cancer." (PMID 34503223, 2021). "The reasons for such a discrepancy in mutational rates are unclear, with some studies suggesting alternative mechanisms that may be required for the development of lung cancer in Asians, who seem to have an inherent non-environmental susceptibility to development of EGFR mutations." (PMID 33435440, 2021). "Dopeso reported that EMT-induced upregulation of TGFA can stimulate EGFR, activate SMAD pathway and induce EMT, which forces a positive feedback loop to enhance EMT and metastasis of lung cancer." (PMID 34150632, 2021). "For lung cancer, we collect the status of the National Comprehensive Cancer Network (NCCN) recommended biomarkers: EGFR, ALK, BRAF, ROS1, KRAS, RET, NTRK and PD-L1." (PMID 33572220, 2021). "A decreased phosphorylation of EGFR (Tyr1068) and the down-stream Akt (Ser473) pathway was noted in ANXA1 knockdown with Osimertinib treatment H1975 and H1650 lung cancer cells." (PMID 34439260, 2021). "Then, we sought to determine the correlation between the expression of EGFR and PLK1 and tumorigenesis in lung cancer patients." (PMID 34503223, 2021). "Methyltransferase Like 3 (METTL3), acting as an oncogene in lung cancer, upregulated EGFR and TAZ expression and promoted growth, survival, and invasion of human lung cancer cells." (PMID 34827123, 2021). "Gene 33 expression has an inverse relationship with tyrosine phosphorylation of EGFR and the expression of metalloproteases MMP-2 and MMP-9 in lung cancer cells, suggesting a role of Gene 33 in lung cancer cell migration, invasion, and metastasis." (PMID 34206547, 2021). "First, the high alternations level on chromosome 7 hot zones are in accordance with the overexpression of nearby EGFR, MET, and BRAF genes in glioma, lung cancers, and melanoma." (PMID 34054918, 2021). "YAP also confers resistance to chemotherapeutic agents such as epidermal growth factor receptor (EGFR)-tyrosine kinase inhibitors (TKIs), and anaplastic lymphoma kinase (ALK) inhibitors in lung cancer." (PMID 34202980, 2021). "EGFR+ sEVs can inhibit the function of tumor-specific CD8+ T cells through induced Tregs, thus accelerating the progression of lung cancer." (PMID 34094979, 2021).
lung cancer (continued). "METL3 expression was high in LUAD and promoted the translation of the epidermal growth factor receptor (EGFR) mRNA and hippo pathway effector TAZ mRNA in lung cancer cells, for induction of cell growth, survival, and invasion." (PMID 34179079, 2021). "Another study showed that by inducing TIMP-2 expression and decreasing TGF-1, Wogonin inhibited the activity of MMP-2, APN and EGFR-TPK, activated caspase 3, and played an important role in the metastasis and apoptosis of lung cancer A549 cells." (PMID 34630106, 2021). "We analyzed single-cell sequencing data from the existing research and found that the epithelial cells at the resection margin of lung cancer were more likely to highly activate the genes related to lung cancer, such as KRAS, MET, and EGFR." (PMID 34094930, 2021). "For example, the discovery of MET amplification in a subset of resistant EGFR-mutant lung cancers has now led to promising activity of combination EGFR and MET TKIs in EGFR-mutant lung cancer patients with acquired resistance due to MET amplification." (PMID 34071428, 2021). "Analysis of the expression levels of common immune checkpoints (PD1 and PD‐L1 in our study) and lung cancer driver genes (ALK, EGFR, ROS1, and MET in our study) between two clusters revealed significant differences in PD1, PD‐L1, and MET gene expression." (PMID 34558724, 2021). "TEX secreted by lung cancer cells contain several proteins involved in tumor development, including CD91, Galectin-9, LRG1, EGFR, and Wnt5b." (PMID 33803617, 2021). "EGFR is a well-studied oncogene in lung cancers and gliomas, MET is also a frequent driver in lung cancers, and BRAF is a signature driver gene in melanoma." (PMID 34054918, 2021). "Cetuximab works by blocking EGFR dimerization and when combined with EAIO45 showed antiproliferative responses both in vivo and in vitro models of lung cancer driven by EGFR L858R/T790M and by EGFR L858R/T790M/C797S mutations." (PMID 34829820, 2021). "NNK has also been shown to activate the β2-adrenergic receptor, which transactivates the EGFR and Raf-1/ERK1/2 signaling cascades, both of which are also well characterized for their roles in lung cancer progression and metastasis." (PMID 33351788, 2021). "The Hippo effector YAP confers EGFR‐TKI resistance by many mechanisms including the upregulating AXL and ERK activation in lung cancer." (PMID 33486901, 2021). "Compared to other EGFR inhibitors, AZD9291 exhibited a good capability to inhibit cancer cell growth in a mouse model with brain metastases of lung cancer." (PMID 34063168, 2021). "Data from clinical trials testing combinations of TKIs and IO for efficacy in EGFR and ALK-driven lung cancer patents demonstrate modest increases in response rates as compared to single agent IO." (PMID 34001994, 2021). "Those genes are frequently altered in different cancers, including AKT1, EGFR, KRAS, and STK11 in lung cancer and AKT1, BRCA2, ERBB2, and PIK3CA in Breast cancer." (PMID 34906079, 2021). "Future directions: genetic drivers of brain metastases.—Driver alterations such as those occurring in EGFR and ALK are responsible for tumorigenesis and therefore represent early, seminal genetic events in lung cancer development." (PMID 34859233, 2021). "Based on this information, it was possible to determine that SOX2‐OT increases resistance to EGFR‐TKI‐erlotinib or cisplatin treatment in A549 cells, as well as resistance to therapy in NCI‐H1975 lung cancer cells." (PMID 33433063, 2021). "In this study, we demonstrated that FAM188B knockdown sensitized anoikis of lung cancer cell lines expressing WT-EGFR (A549 and H1299) or TKI-resistant EGFR mutant T790M/L858R (H1975)." (PMID 33440835, 2021). "In summary, our results suggest that IL-1β leads to increased TF formation in lung cancer cells via both Src/EGFR/p42/44 MAPK-dependent and EGFR-independent signaling pathways, with the latter mediated via p38 MAPK and JNK." (PMID 34205482, 2021).
lung cancer (continued). "Knockdown of EGFR mediated by short hairpin RNA (shRNA)–bearing lentiviruses induced enlarged cell size and growth arrest in CL1-5 lung cancer cells." (PMID 34830377, 2021). "For example, in lung cancer, E2 upregulated the expression of osteopontin (OPN), which contributes to the cross-talk between the ER and EGFR signaling pathways and estrogen-promoted cell migration through activating ERβ of the MEK/ERK signaling pathway." (PMID 33996538, 2021). "Small molecular inhibitors, effecting on KRAS, EGFR, ALK in lung cancer 11, BRAF and MEK in melanoma cells 63, elicit concurrent GSDME-mediated PCD." (PMID 34335940, 2021). "Another study on both μOR and δOR expression in lung cancer revealed that siRNA down regulation of either receptor decreased EGFR activation by EGF and EGFR transactivation by morphine." (PMID 35004315, 2021). "It has been reported that HNK can induce EGFR degradation by inhibiting heat shock protein 90 (HSP90), a molecular chaperone, in lung cancer cells, and in subcutaneously implanted mouse models." (PMID 33806040, 2021). "With the advancement of therapeutic strategies, epidermal growth factor receptor tyrosine kinase inhibitors (EGFR-TKI) and immune checkpoint inhibitors were used for the first-line treatment of patients with lung cancer." (PMID 35096055, 2021). "Erlotinib (ER), as an epidermal growth factor receptor (EGFR) tyrosine kinase inhibitor (TKI), has a significant therapeutic effect in lung cancers." (PMID 34368128, 2021). "NSCLC exosomal proteome has identified the enriched protein cargoes such as EGFR, GRB2 and SRC for lung cancer early detection." (PMID 33504342, 2021). "Germline EGFR mutations may not contribute to early onset of lung cancer." (PMID 34869019, 2021). "In the tested lung cancer cell lines, the metabolic use of glucose differed between EGFR-TKI-sensitive and EGFR-TKI-resistant lung cancer cells." (PMID 34367462, 2021). "The least caspase-inducing effect was found in EGFR-mutant HCC827 cells (Vmax = 10–20), which suggests that EGFR-mutant lung cancer cells are possibly the least vulnerable to caspase induction by RESV." (PMID 33652978, 2021). "Therefore, EphB4 could play an important role in tumor growth in lung cancer, but the association between EphB4 and EGFR mutations or EGFR-TKIs in lung cancer has not been reported thus far, to the best of our knowledge." (PMID 34445227, 2021). "Epidermal growth factor receptor (EGFR) inhibitors, such as erlotinib, are used in the treatment of EGFR-driven lung cancer." (PMID 33808242, 2021). "In vitro, treatment of EGFR mutant lung cancer cells with erlotinib induces Sox-2 expression, with SOX2 knockdown resulting in increased erlotinib-mediated apoptosis and delayed resistance to EGFR inhibition." (PMID 34546978, 2021). "Effective therapies have been currently developed to target EGFR, KRAS, and MET; however, the prognosis of patients with advanced lung cancer remains unsatisfactory." (PMID 33981850, 2021). "The discovery of EGFR, ALK and other driving genes in lung cancer provides an example for targeted therapy of malignant tumors." (PMID 33585082, 2021). "We further focused on the clinical relevance between expression of EGFR/PLK1 and survival rates in lung cancer patients." (PMID 34503223, 2021). "In most cases, we were able to obtain primary lung cancer samples of sufficient quality using ENB-guided biopsy to perform molecular testing, including EGFR, ALK, and PD-L1." (PMID 34441366, 2021). "Studying the relationship between EGFR and the TCR repertoire improves understanding about the application of immunotherapy in lung cancer." (PMID 33777727, 2021). "Lung cancer CL1 and A549 cells stably transfected with α1,3-Fuc-transferases FUT4 or FUT6 showed reduced EGFR dimerization and phosphorylation upon EGF induction." (PMID 34069424, 2021).
lung cancer (continued). "Of note, the ratio of secondary to de novo metastatic EGFR+ NSCLC, approximately 1:4 in our study, itself is not a purely biological characteristic either, but also influenced by the efficacy of lung cancer detection strategies." (PMID 33898315, 2021). "However, it is presently impossible to ascertain the clinical prevalence of single-agent MET dependency in EGFR-mutant lung cancer, because genotyping of lung cancers is most often based on DNA sequencing, which would not capture diminished expression of the mutant EGFR allele." (PMID 34516823, 2021). "The development of EGFR tyrosine kinase inhibitor (TKI), as the therapeutic agent, radically overturned the conventional chemotherapy regimen for lung cancer, which was treated with cytotoxic anticancer agents until then." (PMID 34831415, 2021). "In the last decade, numerous studies have demonstrated that targeted drugs, mainly EGFR and ALK inhibitors, are very effective for treating genetically defined lung cancer patients." (PMID 34858498, 2021). "Following EGFR signaling interception by estrogens, several downstream signaling pathways such as MEK/ERK and PI3K/AKT were activated which promote lung cancer metastasis via epithelial–mesenchymal transition." (PMID 35008242, 2021). "With the popularity of lung cancer screening and advances in imaging technology, more and more synchronous multiple primary lung adenocarcinomas (SMPLA) are being diagnosed clinically, however, the clinical characteristics and prognosis of SMPLA with different EGFR mutations remains unclear." (PMID 35096585, 2021). "Aberrant activation of the epidermal growth factor receptor (EGFR/ERBB1) by erythroblastic leukemia viral oncogene homolog (ERBB) ligands contributes to various tumor malignancies, including lung cancer and colorectal cancer (CRC)." (PMID 34884633, 2021). "Brigatinib, a dual-target inhibitor of EGFR and anaplastic lymphoma kinase, was reported to overcome AZD9291 resistance presented with EGFR C797S in lung cancer." (PMID 34572484, 2021). "Lung cancer is the leading cause of cancer-related deaths in the world, and mutations and deregulation of many proteins and pathways, including EGFR, ALK, ROS1, and MET, play a significant role in lung cancer occurrence and development." (PMID 34603447, 2021). "In the example of the EGFR-RAS-RAF pathway, which is most crucial for lung cancer progression, 101 among 169 phosphosites are class 1 phosphosites." (PMID 33953186, 2021). "To further examine the effect of a combined EGFR plus TNF inhibition in an immunocompetent model, we used a well-established transgenic mouse model of lung cancer that is driven by doxycycline-mediated induction of the EGFR L858R mutation." (PMID 34853306, 2021). "For instance, drug-induced tumor apoptosis may occur for EGFR-targeted therapy in lung cancer within days of initial dosing, and daily sampling of ctDNA may facilitate early assessment of patient response within the first week of treatment with EGFR inhibitors." (PMID 34298813, 2021). "A study in 3D lung cancer cell models revealed that ECM-induced ERK and PI3K/AKT signaling lead to an EGFR TKI tolerant dormant state." (PMID 33170304, 2021). "Osimertinib, a third-generation EGFR-TKI, strongly inhibited H1975 cell proliferation but marginally affected cell proliferation in the lung cancer cell lines with acquired EGFR-TKI resistance (HCC827 GR, H1993 ER, and H292 ER)." (PMID 34367462, 2021). "FGFR aberrations have also been identified as key compensatory bypass mechanisms of resistance to targeted therapy against mutant epidermal growth factor receptor (EGFR) and mutant Kirsten rat sarcoma 2 viral oncogene homolog (KRAS) in lung cancer." (PMID 34068816, 2021). "We demonstrated that combination EGFR blockade and STAT3 inhibition was more effective in inhibiting TKI resistant lung cancer cell xenograft growth than inhibition of either pathway alone." (PMID 33391507, 2021).